LEP (leptin)
Diseases named in the same sentence as LEP in open-access papers (continued):
Sharing a sentence is not in itself a finding about the gene and the disease.
Obesity (continued). "Future studies are warranted to incorporate genetic variants of other cytokines from adipocytes (e.g., leptin) to unravel the complexity of the underlying mechanisms between obesity and breast cancer risk among AA women." (PMID 34367982, 2021). "This is elucidated as leptin is linked with obesity, IR, myocardial infarction and congestive heart disease." (PMID 34209146, 2021). "We found a negative association between miR-6803-3p and leptin levels and positive association between leptin and obesity indicators." (PMID 34440082, 2021). "Because we found differentially expressed leptin levels between obese cases and normal controls, we evaluated the relations among the four obesity-associated miRNAs, obesity-associated mRNAs, and obesity indicators with leptin protein." (PMID 34440082, 2021). "Obesity-driven inflammation has further shown associations with trophoblast development and function in animal models, where leptin and low-density lipoproteins are able to regulate trophoblast apoptosis, proliferation, and migration in culture." (PMID 33572203, 2021). "Data across a range of experimental animal models has highlighted that maintenance of a critical leptin level during early life plays a key role in reducing obesity risk in later life." (PMID 34124118, 2021). "It has been established that leptin and adiponectin ratios are altered in obesity, and adiponectin is associated with protection against insulin resistance in hepatocytes and visceral adipocytes, and adiponectin levels are predictive of NAFLD34." (PMID 34162924, 2021). "Leptin-deficient ob/ob mice (also called ob mice) develop extreme hyperphagia and obesity, and these abnormalities are corrected by leptin treatment." (PMID 33753517, 2021). "Poor sleepers tend to have a higher risk of obesity and type 2 diabetes as suppression of slow-wave sleep leads to decreased insulin sensitivity and leptin levels and increased ghrelin." (PMID 34612827, 2021). "In the present study, we tested the potential association of maternal obesity (primary exposures: BMI, leptin) with fasting fatty acids concentrations in the first trimester of human pregnancy." (PMID 34638763, 2021). "We focused our study on the premise that the meta-inflammation associated with obesity is responsible for developing this disease and taking leptin as the central adipokine in this process." (PMID 34568404, 2021). "In influenza infection, leptin resistance is a major infection susceptibility factor in individuals with obesity by quashing the countenance of IFN-α, IFN-β, IFN-γ mRNAs, and memory T cells." (PMID 34220807, 2021). "The genetically leptin-deficient or leptin-resistant animals or humans develop profound obesity because of hormonal and immune system abnormalities." (PMID 34220807, 2021). "In particular, genome-wide association studies have investigated the influence of specific genetic loci in the pathophysiology of obesity, identifying different LEP and LEPR polymorphisms and measuring their impacts on adiposity development." (PMID 34208585, 2021). "The satiety adipokine leptin is strongly associated with obesity, insulin resistance, and metabolic dysfunction and has been proposed to be pathogenic in IIH." (PMID 33848268, 2021). "Our findings indicated that the obesity-related gene LEP methylation is associated with LEP inactivation, and acts as an independent prognostic predictor in AML." (PMID 33485366, 2021). "C. minuta DSM33407 protected from diet-induced obesity and regulated associated metabolic markers such as glycemia and leptin." (PMID 33917566, 2021). "The presence of p.Asn103Lys leptin mutation was also investigated in the Pakistani population since Pakistan is the 9th country among 188 countries in obesity ranking." (PMID 34504472, 2021). "Although genetic defects affecting leptin signaling cause obesity, such individuals are fairly rare." (PMID 34680059, 2021).
Obesity (continued). "Noteworthy, failure in ovarian leptin signaling in late obesity was associated with the repression in NLRP3 activity, but with maintenance of inflammation and levels of IL-1β." (PMID 34805147, 2021). "Obesity is defined as abnormal or excessive fat accumulation that can be detrimental to health, and is associated with decreased sensitivity to leptin, resulting in an inability to detect satiety despite high energy stores and high levels of leptin." (PMID 34281221, 2021). "Aberrant leptin signaling is a hallmark of obesity and has been recognized to influence BC biology within TME, showing the potential of serving as a biomarker for BC risk in overweight/obese women." (PMID 34350120, 2021). "Leptin functions as a signal to circulate energy reserves by providing feedback inhibition in the hypothalamic orexigenic pathway; thus, obesity is strongly associated with hyperleptinemia." (PMID 34327017, 2021). "In obesity, leptin resistance caused by hyperleptinemia can limit muscle fatty acid oxidation and reduce lipolysis of adipose tissue." (PMID 33807959, 2021). "In patients with obesity associated diabetes, elevated leptin levels lead to increased aromatase and estrogen production, release of pro-inflammatory cytokines, cell proliferation, migration and invasion." (PMID 34225729, 2021). "Insulin resistance is often associated with obesity and hyperleptinemia and leads to increased expression of the obesogenic gene and increased leptin level." (PMID 34039404, 2021). "Of the twenty-five studies where blood lipids were measured, seventeen used animal models of obesity (leptin deficient ob/ob mice or animals with DIO)." (PMID 34505561, 2021). "Leptin, acting within the brain, can increase blood pressure in pre-clinical studies and it can contribute to the hypertension associated with obesity." (PMID 33679451, 2021). "It is conceivable that immunometabolic imbalance due to dysregulated insulin/IGF and leptin signaling pathways underlie immunodeficiency and infection susceptibility in nutritional imbalance, including malnutrition and obesity." (PMID 34795562, 2021). "Combined, these data suggest that increased insulin and leptin in conjunction with decreased adiponectin in the context of obesity likely shifts the balance towards a more pathogenic/pro-inflammatory environment." (PMID 35822048, 2021). "Genetic deficiency of leptin or leptin receptors results in hyperphagia and severe obesity in both rodents and humans." (PMID 34035808, 2021). "We present Med1, an important subunit of the human mediator complex, as the key node of leptin action that associates with obesity-signature genes." (PMID 34389732, 2021). "TNF-α is a classic proinflammatory factor that causes hypothalamic insulin and leptin resistance and is believed to be a contributor to the development of obesity." (PMID 34275474, 2021). "In the course of weight regain among people with obesity, its role is particularly essential, since body weight reduction reduces leptin concentrations and activates NPY, which is associated with hyperphagia and decreased energy usage." (PMID 33530406, 2021). "As such, pathophysiological leptin levels appear to be the primary trigger for augmented vasculopathy associated with diabetes and obesity." (PMID 34064112, 2021). "Since the diabetes (db) gene encodes the receptor for the obese (ob) gene product, leptin, mutations in the mouse db gene, cause leptin dysfunction, resulting in obesity and diabetes in a syndrome similar to that of human obesity." (PMID 33671768, 2021). "A deficiency of leptin signaling as a result of mutations of the leptin gene or its cognate receptor causes hyperphagia and severe obesity in both humans and animals, which clearly demonstrates that normal body-weight requires intact leptin regulation." (PMID 34680059, 2021). "In conclusion, the associations of the MC4R and LEP gene polymorphisms with obesity-related parameters strengthened with age." (PMID 34205732, 2021).
Obesity (continued). "In humans, mutations of leptin with severe early onset of obesity and hyperphagia has been diagnosed in fewer than 100 patients worldwide." (PMID 33922961, 2021). "Single nucleotide polymorphism (SNPs) in the FTO gene were associated with other obesity traits (e.g., body weight, leptin levels, body fat, waist circumference)." (PMID 34743743, 2021). "Obesity is clearly associated with the levels of hormones, such as leptin, adiponectin and resistin secreted from adipose tissue." (PMID 33830560, 2021). "It is well known that obesity is associated with an increase in circulatory leptin levels and prompts a condition of leptin resistance." (PMID 34047810, 2021). "Accordingly, leptin-deficient ob/ob mice have severe hyperphagic obesity, hyperglycemia, and fatty liver." (PMID 34064308, 2021). "Energy balance is regulated through the suppression of hunger, and deficiencies in leptin are often associated with obesity in both mice and humans." (PMID 33498462, 2021). "Our study aimed to explore the underlying mechanisms by which leptin reduces the N6-methyladenosine (m6A) methylation of Plin5 through fat mass and obesity associated genes (FTO) and regulates the lipolysis." (PMID 34638947, 2021). "Studies carried out in rats fed HFDs have shown that leptin locally leads to heart alterations associated with obesity through induction of collagen production, which is mediated by oxidative stress and by the mTOR signaling pathway." (PMID 33809061, 2021). "This implies that the feeding control of body fat mass and obesity is ultimately linked to the downregulation and stabilization of leptin production." (PMID 34884416, 2021). "Leptin involves the regulation of satiety and body weight and is positively associated with obesity, fat mass, insulin resistance, triglyceride levels, and inflammatory cytokines." (PMID 34368053, 2021). "The genetic contribution of obesity has been explored experimentally in the ob (mutation in the gene encoding leptin) and db (mutation in gene encoding leptin receptor) mouse models." (PMID 34777390, 2021). "In obesity, the increase in leptin levels is associated with the state of leptin resistance, in addition to the increase in reactive oxygen species (ROS), IL-6, TNF-α, and chemokines." (PMID 33807959, 2021). "An earlier study demonstrated that high leptin levels were associated with a low risk of diabetes after adjusting for obesity, adiponectin, triglyceride, hypertension, and inflammation scores." (PMID 34368053, 2021). "Discordant results were found regarding the correlation between leptin’s breast milk concentration and the risk of obesity later in life." (PMID 34682128, 2021). "Consistent with hyperleptinemia being causal to obesity, the group of Philipp Scherer demonstrated that normalisation of hyperleptinemia is sufficient to restore leptin sensitivity, drive weight loss, and restore body weight homeostasis." (PMID 34613819, 2021). "Obesity causes leptin and insulin resistance and is accompanied by systemic low-grade inflammation, causing high levels of proinflammatory cytokines and a hampered cellular response to viral infections." (PMID 34668738, 2021). "In the leptin-deficient state (T0), all patients had severe obesity with a mean BMI-SDST0 of 4.14 ± 1.51." (PMID 34002033, 2021). "Altered maternal and placental hormones, particularly leptin, are implicated in the reduced cervical ripening and inhibited myometrial contractility in women with obesity." (PMID 33377279, 2021). "Hyperphagia and obesity are caused by a reduced expression of leptin signaling molecules such as the OBRb in the ARC." (PMID 35153807, 2021). "In general, it is expected that positive impacts of probiotics on obesity and associated metabolic disorders are related to a decrease in serum leptin values or leptin expression." (PMID 34568404, 2021).
Obesity (continued). "The effect of leptin deficiency was first observed in the severely obese (ob/ob) mice, which have a leptin mutation, triggering many comorbidities such as obesity, hyperinsulinemia, corticosterone excess, and infertility." (PMID 34504472, 2021). "In vivo, we investigated two different mouse models of metabolic disease, obesity in leptin-deficient ob/ob mice and obesity achieved via feeding with a high-fat diet." (PMID 33157254, 2021). "Hypoadiponectinemia in obesity is associated with increased leptin, IR, impaired glucose and fat metabolism, and consequently, hyperglycemia and increased fat accumulation." (PMID 34578869, 2021). "Genetic causes of obesity can be broadly classified as: 1) monogenic causes that result from a single gene mutation, primarily located in the leptin- melanocortin pathway." (PMID 34552557, 2021). "The identified associations of MC4R and LEP polymorphisms with obesity-related parameters should be considered as risk factors for age- and gender-related obesity development." (PMID 34205732, 2021). "In fact, exercise training in people with obesity is associated with increased circulating adiponectin and reduced leptin levels." (PMID 33572989, 2021). "On the other hand, exposure to blue light significantly reduces the serum leptin and L/A levels, which suggests the optimization of lipid generation and a reduced risk of obesity." (PMID 34901103, 2021). "During obesity progression, the ever-growing adipose tissue secretes large amounts of leptin, which causes systemic hormonal imbalance." (PMID 33924072, 2021). "This suggested that moderate-load exercise improved leptin resistance and inflammatory reaction and alleviated the HH symptoms caused by obesity." (PMID 33472656, 2021). "Concentrations of IGF-2, the key PLAG1 target gene, were shown to be higher in children with obesity compared to the control group, and were found to be associated with increased leptin levels in adult, normal-weight patients." (PMID 34684585, 2021). "It was also suggested that BDV infection-induced neuroinflammation and neurotransmitter imbalance underlie the dysfunction of hypothalamus and leptin resistance, leading to obesity." (PMID 34795562, 2021). "Increased circulating leptin is associated with obesity and increased cancer risk; thus, leptin-mediated regulation of PC activity is particularly interesting, considering the increased mortality from cancer observed in obese individuals." (PMID 33931119, 2021). "Metreleptin is a recombinant methyl-human leptin hormone showing efficacy in children with congenital leptin deficiency reversal of obesity and metabolic improvement." (PMID 33807959, 2021). "In rodents, LepR gene mutations result in leptin-insensitivity, which ultimately leads to development of early-onset obesity as well as several endocrine-related impairments." (PMID 33440796, 2021). "Leptin levels are directly proportional to the amount of body fat and therefore obesity is usually associated with hyperleptinemia and leptin resistance." (PMID 34832862, 2021). "Normalization of leptin sensitivity has been proposed as an efficient strategy to reinforce weight loss and avoid weight regain in treatments for obesity." (PMID 34899599, 2021). "Alterations in leptin signaling are closely associated with metabolic diseases, such as obesity and T2D." (PMID 34183063, 2021). "•RYGB surgery-related weight loss independently restores hypothalamic leptin signaling and action in diet-induced obesity." (PMID 33741533, 2021). "Increased leptin levels of patients with obesity contribute to chronic low-grade inflammation associated with obesity, which is believed to promote several obesity related diseases such as type-2 diabetes, autoimmune diseases, and cardiovascular diseases." (PMID 33824998, 2021). "The proband had the classical features observed in obesity caused by congenital leptin deficiency, with leptin level close to limit detection." (PMID 34504472, 2021).
Obesity (continued). "Immune dysregulation and disturbances in hormones (i.e. leptin) in patients with obesity have been proposed as the main mechanisms underlying increased susceptibility to influenza viruses." (PMID 33913410, 2021). "Unfolded protein response (UPR) caused by ER dysfunction is known as ER stress, which is related to metabolic diseases including insulin resistance and obesity because induced ER stress prevents weight loss and anorexic functions of insulin and leptin." (PMID 33763034, 2021). "Serum and cord blood stored for biomarkers such as leptin, adiponectin and placental hormones provides opportunities to identify infants at an earlier stage who are at risk of obesity in childhood." (PMID 33807319, 2021). "Fragmented mitochondria generate more ROS and induce ER stress; ER stress has been linked to leptin resistance and obesity." (PMID 34231322, 2021). "Leptin, a key regulator between energy metabolism and immune system, is also responsible in part for the obesity linked inflammatory state." (PMID 34535145, 2021). "Similar to insulin resistance, there was resistance to leptin in obesity caused by excessive leptin content in serum and impaired energy homeostasis, leading to increased food intake and weight gain." (PMID 33585429, 2021). "Comparable to leptin deficient ob/ob mice, mutations in the Lepr cause obesity in Leprdb/db mice and other models." (PMID 34390703, 2021). "Jet lag or constant light exposure contributes to leptin resistance (a hallmark of obesity), increased adiposity and weight gain." (PMID 34557221, 2021). "But the association between OSAS and serum/plasma leptin levels is intricate and multidirectional because obesity alone can also affect leptin levels." (PMID 34671315, 2021). "Long-term hyperleptinemia, observed in obesity, is associated with decreased natural killer cell immune activity, possibly due to leptin resistance." (PMID 34912237, 2021). "Resistance to the hormones insulin and leptin in the offspring affects the metabolic milieu predisposing the individual to obesity and diabetes." (PMID 34796053, 2021). "The aim of our study was to analyze the role of leptin in the association between obesity and NEFA levels in children." (PMID 35071145, 2021). "Keeping in mind that obesity is one of the risk factors for endometrial cancer, in this study the correlation between BMI and serum leptin concentration was analyzed." (PMID 34202922, 2021). "Genome-wide and candidate genes association studies have shown the role of variants in genes of the leptin-melanocortin pathway on body mass index (BMI), adiposity, and metabolic dysregulation related to obesity and MetS in several populations." (PMID 33540559, 2021). "This suggests an additive effect of ABX and WPI toward reducing leptin levels in HFD‐associated obesity." (PMID 34057306, 2021). "The subjects showing overweight or obesity carried heterozygous LEP variants p.G133Vfs*15, p.R105W, p.N103K, and p.C117F." (PMID 34448070, 2021). "Increased sleep time during childhood has advantageous effects on protecting against a genetic predisposition to obesity, with leptin playing a key role in the process." (PMID 34631629, 2021). "Currently, only eight different mutations in LEP that are thought to cause severe obesity have been reported." (PMID 34208585, 2021). "Elevated levels of leptin have been associated with obesity, psychological distress, increasing systemic inflammation, increasing risk in the development of several maligniances (colon, ovarian cancer, prostate, and breast cancers)." (PMID 34173157, 2021). "Disruption of the leptin signaling axis in animal models leads to obesity and leptin resistance is a hallmark of metabolic disorder in humans." (PMID 34283042, 2021). "Increased leptin in obesity increases the phagocytic function of ATMs and is associated with an increase in circulating C-reactive protein." (PMID 34248937, 2021).